TSPAN6 (tetraspanin 6)
Diseases named in the same sentence as TSPAN6 in open-access papers (continued):
Sharing a sentence is not in itself a finding about the gene and the disease.
cancer (7 papers, 2021 to 2026). A tumor composed of atypical neoplastic, often pleomorphic cells that invade other tissues. "We noted that Tspan6 was listed among genes whose expression is significantly decreased in cancer-associated polyps as compared to cancer-free polyps." (PMID 34521767, 2021). "Our data indicate that the predictive power of Tspan6 expression is linked to the key role played by this protein in modifying the biological activity of EVs secreted by cancer cells." (PMID 34521767, 2021). "Using the pan-cancer atlas of over 4.4 million cells, we revealed the specific expression of TSPAN6 in malignant cells." (PMID 41782878, 2026). "In our validation cohorts, paired serum samples from 44 cancer patients showed significantly decreased TSPAN6 levels following immunotherapy." (PMID 41782878, 2026). "To address the functional role of Tspan6 in Ras-mutant cancers, we first examined the effect of reduced Tspan6 expression in mouse mammary epithelial cells (Eph4) stably transfected with oncogenic H-Ras, termed EpRas cells." (PMID 35184157, 2022). "Our data suggest that the increased expression of EGFR in those tumors will be responsive to the treatment if cancer cells express Tspan6, which suppresses secretion of TGF-α." (PMID 34521767, 2021). "Based on the available evidence, CD81 and CD82, and TSPAN6 can serve as cancer suppressors, while CD151, TSPAN1, and TSPAN8 act as cancer promoters in the diagnosis and prognosis of HCC patients." (PMID 34540692, 2021). "In contrast, TSPAN6 can reduce EV production and the contents in EVs in cancer cells." (PMID 36941633, 2023). "As the function of TSPAN6 in mammalian systems was unknown, in this current study we investigate the role of TSPAN6 in human cell lines and mouse cancer models." (PMID 35184157, 2022). "Finally, the most critical node in the BLCA network was Cg01473187, corresponding to the gene TSPAN6, which is a suppressor of Ras-driven cancer." (PMID 36676027, 2022). "Thus, we propose that Tspan6-dependent sensitization to the EGFR-targeted therapy is due to the suppression of TGF-α secretion by cancer cells." (PMID 34521767, 2021). "Pan-cancer validation across the TCGA, ICGC, and CPTAC cohorts confirmed that elevated TSPAN6 expression significantly correlates with adverse prognosis." (PMID 41782878, 2026). "However, the role of Tspan6 in cancer is completely unknown." (PMID 34521767, 2021). "For example, TSPAN6 could bind with EGFR and inhibit its downstream KRAS-ERK1/2 signaling to suppress KRAS-driven cancer initiation and metastasis." (PMID 36941633, 2023). "Altogether, TSPAN1, TSPAN15, TSPAN29, and CD151 could support cancer cell growth, while TSPAN31, TSPAN6, CD9, CD37 could inhibit cancer growth." (PMID 36941633, 2023).
adenocarcinoma (2 papers, 2021 to 2022). A common cancer characterized by the presence of malignant glandular cells. "At 16 weeks after Ad-Cre infection, knockout of Tspan6 resulted in markedly increased progression to adenocarcinomas." (PMID 35184157, 2022). "In this analysis, we found that the survival of patients with high TSPAN6-expressing adenocarcinomas was significantly better compared to patients with low TSPAN6-expressing adenocarcinomas." (PMID 34521767, 2021).
TSPAN6 also shares sentences with these, for which no sentence is quoted: aortic valve disease (1 paper); cognitive diseases (1); colon cancer (1); colorectal tumor (1); coronary atherosclerosis (1); infection (1); ischemic heart disease (1); osteosarcoma (1); Rett syndrome (1); viral infection (1).